LINC01138 (long independently transcribed non-coding RNA 1138)
Synonyms: FLJ39739; MP60; LINC00875; LINC01731; LOC105371225
Gene: Long non-coding RNA gene on chromosome 1 (148,254,495 to 148,529,415, reverse strand). Ensembl gene ENSG00000274020.
Gene Ontology:
Molecular function: pre-mRNA 5'-splice site binding; triplet codon-amino acid adaptor activity
Biological process: mRNA 5'-splice site recognition; translation
Cellular component: U1 snRNP
Diseases named in the same sentence as LINC01138 in open-access papers:
LINC01138 is named in the same sentence as 10 diseases in open-access papers, as found by Europe PMC text mining. Sharing a sentence is not in itself a finding about the gene and the disease. The quoted sentences say what the papers report.
hepatocellular carcinoma (5 papers, 2019 to 2023). A malignant tumor that arises from hepatocytes. "For example, upregulated LINC01138 promoted cell growth and was considered a prognostic indicator in hepatocellular carcinoma, clear cell renal cell carcinoma, and gastric cancer." (PMID 35726651, 2023). "For example, LINC01138 specifically binds with PRMT5 in hepatocellular carcinoma cells, and this association may be a potential therapeutic target in hepatocellular carcinoma." (PMID 31186036, 2019). "LINC01138 regulates the expression of downstream genes through modulating protein arginine methyltransferase 5 (PRMT5), promoting hepatocellular carcinoma (HCC) cell proliferation, tumorigenicity, tumor invasion, and metastasis in vitro and in vivo." (PMID 34745388, 2021). "IGF2BP3 could promote the interaction between LINC01138 and PRMT5 by combining with LINC01138 and ultimately increase PRMT5 stability in hepatocellular carcinoma." (PMID 35676262, 2022). "LINC01138 induces malignancies via activating arginine methyltransferase 5 and interacting with PRMT5 to promote SREBP1-mediated lipid desaturation individually in hepatocellular carcinoma and clear cell renal cell carcinoma." (PMID 31433789, 2019).
clear cell renal cell carcinoma (4 papers, 2019 to 2024). "We designed siRNAs for LINC01138 and LINC01605 to silence the expression of LINC01138 and LINC01605 in human renal clear cell carcinoma cell lines 769-P and 786-O cells to investigate the roles of LINC01138 and LINC01605 in renal clear cell carcinoma." (PMID 39167430, 2024). "We experimentally confirmed the role of LINC01138 and LINC01605 in renal clear cell carcinoma." (PMID 39167430, 2024). "LINC01138 and LINC01605 knockdown inhibited the proliferation of renal clear cell carcinoma." (PMID 39167430, 2024).
liver cancer (3 papers, 2018 to 2023). An epithelial or non-epithelial malignant neoplasm that arises from the liver. "LINC01138 promotes malignant behaviors by activating arginine methyltransferase 5 in liver cancer cells, revealing LINC01138/PRMT5 axis as an ideal target for liver cancer treatment." (PMID 36081999, 2022). "Moreover, LINC01138 is widely expressed in different liver cancer cell lines and distributes in both the cytoplasm and nucleus of SMMC-7721, SNU-449 and Huh-7 cells." (PMID 29679004, 2018).
glioma (1 paper, 2024). A benign or malignant brain and spinal cord tumor that arises from glial cells (astrocytes, oligodendrocytes, ependymal cells). "The lncRNA LINC01138 functions as an oncogenic driver; its silencing inhibits aerobic glycolysis via regulation of the microRNA-375/SP1 axis, thereby decreasing glioma cell proliferation." (PMID 39167430, 2024).
lung carcinoma (1 paper, 2022). "Silencing LINC01138 repressed viability, proliferation, and metastasis of A549 and H460 cells, indicating that LINC01138 was an oncogene in lung cancer." (PMID 36060239, 2022). "Additionally, our study clarified the biological function of LINC01138 in tumorigenesis, indicating that it could promote malignant behaviors in lung cancer." (PMID 36060239, 2022).
tumor (9 papers, 2016 to 2025). "With the intersection of these 53 candidate lincRNAs with relative HCC genomic gains and the 1082 lincRNAs upregulated in the TCGA cohort of 50 paired HCC tissues and adjacent non-tumour (NT) tissues, four lincRNAs were identified, namely, LINC01138, PVT1, RP11-14N7.2 and RP11-30J20.1." (PMID 29679004, 2018). "LINC01138 acts as an oncogenic driver that promotes cell proliferation, tumorigenicity, tumour invasion and metastasis by physically interacting with arginine methyltransferase 5 (PRMT5) and enhancing its protein stability by blocking ubiquitin/proteasome-dependent degradation in HCC." (PMID 29679004, 2018). "Moreover, LINC01138 has been reported as a tumor promoter that can exert its biological functions via the tumor-related IGF2BP1/IGF2BP3-LINC01138-PRMT5 axis in hepatocellular carcinoma (HCC), which can serve as a robust biomarker and therapeutic target for HCC." (PMID 35506372, 2022). "In the tumor immune microenvironment, high expression of LINC01138 and LINC01605 showed low tumor purity, high immune score, high stromal score and high ESTIMATE score." (PMID 39167430, 2024). "The expression levels of AC024060.2, LINC01138, AL034550.1, SNHG12, and AP001347.1 were upregulated in tumor tissues compared with those in the adjacent normal tissues." (PMID 35726651, 2023). "LINC01138 acts as an oncogene and significantly promotes HCC cell proliferation, tumorigenicity, tumour invasion and metastasis in vitro and in vivo." (PMID 29679004, 2018). "Our study identified three androgen-responsive lncRNAs, LINC01138, SUZ12P1 and SNHG1 were significantly over-expressed in more metastasis and higher tumor stage patients." (PMID 27556357, 2016).
cancer (5 papers, 2020 to 2025). A tumor composed of atypical neoplastic, often pleomorphic cells that invade other tissues. "The identification of MP60 as a functional micropeptide encoded by a specific LINC01138 transcript expands our understanding of the coding potential of lncRNAs and their implications in cancer biology." (PMID 40941029, 2025). "Long intergenic non‐protein coding RNA 1138 (LINC01138) plays a vital role in human cancers." (PMID 36705420, 2023). "Among the 12 m6ARLncRNAs, LINC01138, SNHG12, ITGA9‐AS1, and TSPOAP1‐AS1 were involved in malignant phenotypes of cancers." (PMID 35726651, 2023).
LINC01138 also shares sentences with these, for which no sentence is quoted: gastric cancer (2 papers); herpesvirus infection (1); prostate carcinoma (1).